BRD3OS (BRD3 opposite strand)
Synonyms: LINC00094; NCRNA00094; SERLOC; FLJ35348; bA374P20.3; LP2477
Gene: Protein-coding gene on chromosome 9 (134,025,429 to 134,034,666, forward strand). Ensembl gene ENSG00000235106.
Subcellular location (Human Protein Atlas): Nucleoli; Nucleoplasm; Cytosol; Vesicles
Homologues: Orthologues: chimpanzee BRD3OS (100% identical), pig BRD3OS (95% identical), tropical clawed frog BRD3OS (83% identical).
Diseases named in the same sentence as BRD3OS in open-access papers:
BRD3OS is named in the same sentence as 11 diseases in open-access papers, as found by Europe PMC text mining. Sharing a sentence is not in itself a finding about the gene and the disease. The quoted sentences say what the papers report.
lung carcinoma (3 papers, 2019 to 2022). "On the other hand, BRD3OS (LINC00094) has been shown to be downregulated in lung cancer compared to normal tissue." (PMID 36010973, 2022).
cutaneous squamous cell carcinoma (2 papers, 2022 to 2024). "The role of SE-regulated lncRNA-LINC00094 of BRD3OS (named SERLOC by the authors) was also shown in cutaneous squamous cell carcinoma (CSCC)—the most common metastatic skin cancer." (PMID 38542080, 2024). "We examined the role of BRD3OS, also named LINC00094, in cutaneous squamous cell carcinoma (cSCC)." (PMID 36010973, 2022).
esophageal cancer (1 paper, 2022). A primary or metastatic malignant neoplasm involving the esophagus. "BRD3OS (LINC00094) has been shown to be expressed by esophageal cancer (ESCC) cells and to induce the growth and survival of these cancer cells." (PMID 36010973, 2022).
esophageal SCC (1 paper, 2022). "BRD3OS (LINC00094) expression has been previously shown to be regulated by a super enhancer (SE) in esophageal SCC." (PMID 36010973, 2022).
cancer (3 papers, 2020 to 2022). A tumor composed of atypical neoplastic, often pleomorphic cells that invade other tissues. "In previous studies, BRD3OS (LINC00094) has been shown to be upregulated during cancer progression." (PMID 36010973, 2022). "It is tempting to suggest that in cSCC cells where ERK1/2 activity is low, BRD3OS (LINC00094) expression is elevated, and the increased expression of this lncRNA then promotes the invasion of these cancer cells." (PMID 36010973, 2022). "Based on these observations, BRD3OS (LINC00094) was named SERLOC (super enhancer and ERK1/2-Regulated Long Intergenic non-protein coding transcript Overexpressed in Carcinomas)." (PMID 36010973, 2022).
tumor (2 papers, 2021 to 2022). "Lastly, cSCC cells were transfected with BRD3OS siRNA and negative control siRNA and injected subcutaneously into the back of the SCID mice for studying the role of BRD3OS (LINC00094) in tumor growth in vivo." (PMID 36010973, 2022). "Increased expression of BRD3OS (LINC00094) was noted in tumor cells in cSCCs and their metastases compared to normal skin, actinic keratoses, and cSCCs in situ." (PMID 36010973, 2022). "The expression level of BRD3OS (LINC00094) is markedly upregulated in tumor cells in UV-induced primary cSCCs and in their metastases compared to normal skin, and precancerous forms of actinic keratosis (AK) and cSCC in situ (cSCCIS)." (PMID 36010973, 2022). "Furthermore, analysis of tissue sections of xenografts established with human cSCC cells (UT-SCC7) with RNA in situ hybridization (RNA-ISH) revealed specific expression of BRD3OS (LINC00094) in tumor cells." (PMID 36010973, 2022). "Additionally, increased expression of BRD3OS (LINC00094) was noted in tumor cells in cSCC in vivo compared with normal skin, AK, and cSCCIS." (PMID 36010973, 2022). "BRD3OS (LINC00094) knockdown decreased tumor growth compared with control tumors." (PMID 36010973, 2022). "In normal skin, the expression was weaker than in AK and cSCCIS, The BRD3OS (LINC00094) positive particles in the cytoplasm and nucleus of epidermal and tumor cells were counted, and the tissue samples were classified based on the number of particles in one cell." (PMID 36010973, 2022). "Our results also show that BRD3OS (LINC00094) is not expressed by all cSCC tumor cells in vivo." (PMID 36010973, 2022).
infection (1 paper, 2022). The state of being infected such as from the introduction of a foreign agent such as serum, vaccine, antigenic substance or organism. "Treatment of HaCaT cells with an ERK1/2 inhibitor increased, and infection of HaCaT cells with constitutively active MEK1 adenovirus decreased the expression of BRD3OS (LINC00094)." (PMID 36010973, 2022).
BRD3OS also shares sentences with these, for which no sentence is quoted: Alzheimer disease (1 paper); atherosclerosis (1); breast carcinoma (1); lung squamous cell carcinoma (1).